CCDC150 (coiled-coil domain containing 150)
Synonyms: FLJ39660
Tractability: PROTAC: ubiquitination databases record sites on it.
Gene: Protein-coding gene on chromosome 2 (196,639,554 to 196,763,490, forward strand). Ensembl gene ENSG00000144395.
Subcellular location (Human Protein Atlas): Nucleoplasm
Gene Ontology:
Molecular function: protein binding
Genetic constraint (gnomAD): Loss-of-function variants: 97 observed, 103.22 expected, observed/expected ratio (o/e) 0.94, 90% interval 0.8 to 1.11. The upper end of that interval is the gene's LOEUF score, 1.11, which puts it in group 4 of 6, group 1 being the genes least tolerant of losing a copy. Missense variants: 957 observed, 954.89 expected, observed/expected ratio (o/e) 1, 90% interval 0.95 to 1.06. Synonymous variants: 341 observed, 328.67 expected, observed/expected ratio (o/e) 1.04, 90% interval 0.95 to 1.13.
Homologues: Orthologues: chimpanzee CCDC150 (99% identical), macaque CCDC150 (97% identical), rabbit CCDC150 (85% identical), dog CCDC150 (84% identical), pig CCDC150 (81% identical), mouse Ccdc150 (77% identical), rat Ccdc150 (76% identical), guinea pig CCDC150 (51% identical), tropical clawed frog ccdc150 (39% identical), zebrafish si:dkey-75b17.1 (30% identical).
Diseases named in the same sentence as CCDC150 in open-access papers:
CCDC150 is named in the same sentence as 5 diseases in open-access papers, as found by Europe PMC text mining. Sharing a sentence is not in itself a finding about the gene and the disease. The quoted sentences say what the papers report.
triple-negative breast carcinoma (1 paper, 2025). An invasive breast carcinoma which is negative for expression of estrogen receptor (ER), progesterone receptor (PR), and human epidermal growth factor receptor 2 (HER2). "Similarly, gradient rotating magnetic fields have been reported to impair F-actin-related gene CCDC150, thereby inhibiting triple-negative breast cancer metastasis by inactivating the TGF-β1/SMAD3 signaling pathway." (PMID 40552270, 2025).
tumor (2 papers, 2021 to 2024). "CCDC150 expression increased significantly in stage I and stage IV tumor nodal metastasis (TNM) compared to stage III." (PMID 38420580, 2024). "Tumor volumes decreased 68.1% (P < 0.001) and 59.93% (P < 0.01) after si-CCDC150 treatment and gradient RMF exposure, respectively." (PMID 38420580, 2024). "Tumor net weights decreased 80.21% (P < 0.001) and 74.83% (P < 0.001) in the si-CCDC150 treatment and gradient RMF exposure groups, respectively, compared to the NC group." (PMID 38420580, 2024). "CCDC150 was up-regulated in TNBC tumor tissues and cell lines, and its elevated expression was negatively correlated to poor clinical prognosis of TNBC patients." (PMID 38420580, 2024). "By comparing the methylation levels of the paired samples, a lower methylation level in CCDC150 in tumor samples was observed." (PMID 35111672, 2021). "Because gradient RMF exposure and CCDC150 knockdown inhibited the migration and invasion capacity of MDA-MB-231 cells, their effects on TNBC tumor growth were validated in vivo." (PMID 38420580, 2024). "We identified a key cytoskeletal gene, CCDC150, which was abnormally elevated in TNBC tumor tissues and markedly down-regulated after gradient RMF exposure." (PMID 38420580, 2024). "Gradient RMF exposure significantly inhibited tumor growth and distal liver metastasis in TNBC tumor-bearing nude mice by inactivating the TGF-β1/SMAD3 signaling pathway through the suppression of CCDC150 expression." (PMID 38420580, 2024). "CCDC150 silencing and gradient RMF exposure both suppressed TNBC tumor growth and liver metastasis." (PMID 38420580, 2024). "After CCDC150 knockdown in MDA-MB-231, BT549, and MDA-MB-468 cells, the polarization coefficient and spreading area of the cytoskeleton were significantly increased, with a substantial inhibition of cell invasion and tumor growth." (PMID 38420580, 2024). "Compared with normal samples, the gene expression of CCDC150 in tumor samples was not significantly changed, but the activities of prmtr.36049 were notably increased." (PMID 35111672, 2021).
cancer (1 paper, 2021). A tumor composed of atypical neoplastic, often pleomorphic cells that invade other tissues. "We reported that the CpG methylation status of CCDC150 and RABGAP1L could have prognostic values in HCC, which linked the functions of these two genes to cancer development." (PMID 35111672, 2021).
CCDC150 also shares sentences with these, for which no sentence is quoted: aneuploidy (1 paper); breast carcinoma (1).